HTT (huntingtin)
Diseases named in the same sentence as HTT in open-access papers (continued):
Sharing a sentence is not in itself a finding about the gene and the disease.
Huntington disease (continued). "Huntington's disease (HD) is a fatal neurodegenerative disorder characterized by striatal neurodegeneration, the accumulation of mutant huntingtin (mHTT), and the presence of reactive astrocytes." (PMID 40166646, 2025). "HD, also known as Huntington’s chorea, is caused by a CAG trinucleotide repeat amplification in the HTT gene on chromosome 4." (PMID 40002740, 2025). "An uncommon genetic condition known as Huntington’s disease (HD) is brought on by an increase in CAG trinucleotide repeats in the gene (i.e., huntingtin) that encodes for this protein." (PMID 41180498, 2025). "PolyQ-expanded Ataxin-2 abundance in biofluids would be an obvious candidate biomarker for SCA2, similar to what was described for huntingtin or Ataxin-3 proteins in Huntington ́s disease (HD) or SCA3, respectively." (PMID 41298695, 2025). "The linked associations of HTT and its regulator GPR52 highlight a clear repurposing opportunity, as GPR52 is already an investigational drug target for Huntington’s disease." (PMID 41001472, 2025). "Mutant huntingtin (mHTT) aggregates represent a key pharmacodynamic biomarker of Huntington's disease (HD)." (PMID 41257000, 2025). "In Huntington’s disease, metformin shows promise through its effects on mutant huntingtin protein levels and mitochondrial function." (PMID 40283923, 2025). "In particular, improved AAVs for targeting medium spiny neurons and lowering huntingtin for Huntington’s disease treatment have recently emerged." (PMID 39881338, 2025). "Huntington’s disease, or Huntington’s chorea, is a fatal neurodegenerative disease inherited dominantly and associated with expansion of CAG repeats in the HTT gene, which encodes the protein huntingtin." (PMID 40650152, 2025). "For example, CPPs were used to disrupt mutant Huntingtin’s (HTT) protein–protein interactions in a Huntington disease model and DJ-1’s (PARK7) interactions in a Parkinson disease model." (PMID 40014573, 2025). "Many NDDs are associated with the accumulation of misfolded or abnormal proteins, such as amyloid-β in Alzheimer’s disease, α-synuclein in Parkinson’s disease, and huntingtin protein in Huntington’s disease." (PMID 41011595, 2025). "Given the pleiotropic actions of CDK5 on numerous neuronal substrates, the precise regulation of HTT phosphorylation at S434 is crucial to balance its physiological and pathological roles, thereby mitigating the progression of Huntington’s disease." (PMID 41303392, 2025). "Huntington's disease (HD) is an inherited neurodegenerative disease caused by a mutation in the HTT gene, which encodes the huntingtin protein (Htt)." (PMID 40959271, 2025). "Other studies have also demonstrated that silencing the murine homolog Supt4h in mouse models of Huntington’s disease led to reduced expression of mutant huntingtin mRNA, decreased formation of polyQ aggregates, and improvement in disease-related phenotypes." (PMID 41337098, 2025). "Huntington’s disease (HD) is a neurodegenerative disorder caused by the expansion of CAG repeats in the HTT gene, which results in a long polyglutamine tract in the huntingtin protein (HTT)." (PMID 40635054, 2025). "One of these is Huntington’s disease, which is caused by an expansion of trinucleotide (CAG) repeats in exon 1 of huntingtin gene (HTT)." (PMID 41511351, 2025). "In Huntington’s disease (HD), mutant huntingtin (mHTT) impairs mitochondrial transport, calcium buffering, and ATP production, increasing susceptibility to apoptosis through mitochondrial permeability transition pore (mPTP) opening." (PMID 40943612, 2025). "Huntington’s Disease (HD) is an autosomal-dominant neurodegenerative disease characterized by expanded trinucleotide CAG repeats in the Huntingtin (HTT) gene on chromosome 4." (PMID 41169989, 2025).
Huntington disease (continued). "In Huntington’s disease, the aggregation of polyglutamine-expanded huntingtin (HTT-polyQ) is a key pathological feature, while in ALS, aggregation of mutant FUS (mutFUS) contributes to neuronal toxicity and disease progression." (PMID 40839310, 2025). "These compounds hold promise for treating neurodegenerative disorders, including branaplam for lowering huntingtin levels in Huntington’s disease." (PMID 40343270, 2025). "It is more commonly linked to Huntington’s disease, which is normally attributed to the expansion of cytosine–adenine–guanine (CAG) repeats in the huntingtin gene." (PMID 40142228, 2025). "Huntington’s Disease arises from an expansion of cytosine-adenine-guanine (CAG) trinucleotide repeats in the HTT gene (formerly IT15) of chromosome 4p16.3, leading to the production of a dysfunctional huntingtin protein (polyQ-HTT)." (PMID 41463559, 2025). "ASOs have been studied in several neurodegenerative diseases, including tau-directed ASOs in Alzheimer's disease and those targeting mutant huntingtin in Huntington's disease." (PMID 41585268, 2025). "Huntington’s disease (HD) is a rare, genetically inherited neurological condition caused by a CAG triplet repeat expansion in the huntingtin gene (HTT) encoding the huntingtin protein (htt)." (PMID 39852353, 2025). "Huntington's disease (HD) is caused by an expansion of a CAG repeat within the HD gene, encoding an expanded stretch of polyglutamines in the mutant huntingtin (mHTT) protein." (PMID 40406043, 2025). "Essential proteins, such as amyloid beta (Aβ) and tau in Alzheimer’s disease (AD), α-synuclein in Parkinson’s disease (PD), and huntingtin in Huntington’s disease (HD), have been identified as major players in this process." (PMID 40537797, 2025). "Huntington’s disease (HD) is a progressive NDD characterized by the expansion of CAG repeats in the huntingtin gene, resulting in a range of symptoms, including neuropsychiatric disturbances, cognitive decline, and involuntary movements." (PMID 40533746, 2025). "In Huntington’s disease, where mutant huntingtin protein aggregates and perturbs synaptic and mitochondrial function, cyclodextrins help restore cholesterol balance and protect against excitotoxicity." (PMID 41155704, 2025). "Huntington's disease (HD) is characterized by the presence of mutant huntingtin toxic oligomers, which induce misfolded protein accumulation in the ER, triggering the UPR pathway." (PMID 39995125, 2025). "Huntington’s disease (HD) is a neurodegenerative disorder that manifests from an expansion of CAG repeats (>36) in the Huntingtin (HTT) gene." (PMID 40263294, 2025). "Lower levels of endogenous UBA1 in the brain also correlate with increased levels of mutant huntingtin protein in a mouse model of Huntington’s disease." (PMID 39773572, 2025). "In Huntington’s disease (HD), involved defective cholesterol and phospholipid metabolism due to mutant huntingtin-induced SREBP dysregulation, compromising synaptic function and neuronal viability." (PMID 40880849, 2025). "In Alzheimer’s and Parkinson’s diseases, PM2.5 exacerbates the accumulation of β‐amyloid, hyperphosphorylated tau, and α‐synuclein, while in Huntington’s disease, it worsens toxicity mediated by mutant huntingtin." (PMID 41498103, 2025). "The HTT gene represents the key locus responsible for the pathogenetic cascade occurring in Huntington’s disease (HD)." (PMID 39572770, 2025). "Huntingtin (HTT) is a very large, well-conserved 348-kDa protein that was discovered for its role in Huntington’s disease (HD), where it contains an abnormal expansion of a polyglutamine tract in its N terminus." (PMID 40971423, 2025). "Huntington’s disease (HD) is an autosomal dominant neurodegenerative disorder caused by a CAG repeat expansion in the huntingtin HTT gene, which encodes the huntingtin protein." (PMID 39911695, 2025).
Huntington disease (continued). "Pediatric Huntington’s disease (PHD), a rare and severe form of juvenile-onset Huntington’s disease (JOHD), is associated with highly expanded CAG repeats in the HTT gene and a rapidly progressive neurodegenerative course." (PMID 40908995, 2025). "Huntington’s disease (HD) is a devastating neurodegenerative disorder that manifests from an N-terminal polyQ-expansion (>35) in the Huntingtin (HTT) gene leading to axonal degeneration and significant neuronal death." (PMID 40263294, 2025). "The primary aggregation-prone proteins involved include amyloid-beta (Aβ) and tau in Alzheimer’s disease (AD), α-synuclein (α-Syn) in Parkinson’s disease (PD), and huntingtin (HTT) in Huntington’s disease (HD)." (PMID 40385290, 2025). "Huntingtin (HTT), a protein central to Huntington’s disease (HD), has emerged as a putative multifunctional regulator within the neuronal autophagy–lysosome pathway." (PMID 40475846, 2025). "Accumulated levels of mutant huntingtin protein (mHTT) and its fragments are considered contributors to the pathogenesis of Huntington’s disease (HD)." (PMID 41204380, 2025). "In the context of Huntington’s disease (HD), SUMOylation occurs predominantly at K6 and K9 of mHTT, which overlap with ubiquitination sites (e.g., K6 and K9 in HTT exon 1)." (PMID 41303392, 2025). "In Huntington’s disease (HD), a neurodegenerative disorder marked by the accumulation of mutant huntingtin (HTT) protein, oxidative stress plays a significant role in neuronal injury." (PMID 40867576, 2025). "Huntington’s Disease (HD) is a fatal genetic neurodegenerative disorder characterized by a CAG triplet repeat expansion in the human huntingtin (HTT) gene, which leads to an increase in function of the mutant huntingtin protein (mHTT)." (PMID 40362450, 2025). "Enhancing autophagy can reduce the levels of mutant huntingtin (mHTT) and promote cell survival in both cellular and animal models of Huntington’s disease (HD)." (PMID 40564109, 2025). "Among neurodegenerative disorders are also polyglutamine (polyQ) diseases, such as Huntington’s disease (HD), the onset of which has been linked to abnormally expanded CAG trinucleotide repeat coding for the polyQ sequence in mutant Huntingtin proteins." (PMID 39596513, 2024). "Huntington’s disease (HD) is a monogenic neurodegenerative disease, caused by the CAG trinucleotide repeat expansion in exon 1 of the Huntingtin (HTT) gene." (PMID 38744826, 2024). "A recent gene therapy modality uses AMT-130 that contains a miRNA to bind and stop the translation of huntingtin mRNA to treat Huntington’s disease (NCT04120493)." (PMID 38558807, 2024). "Huntington’s disease (HD) is a progressive, neurodegenerative disorder caused by an expansion of the CAG triplet repeat of the Huntingtin gene (≥36 repeats), located on the short arm of chromosome 4." (PMID 39797251, 2024). "This table summarizes studies on the interplay between mutant huntingtin, cellular senescence, and aging in Huntington's Disease." (PMID 39428700, 2024). "Examples include targeting the HTT gene in Huntington’s disease or the SMN1 gene in spinal muscular atrophy." (PMID 39684197, 2024). "Huntington’s disease (HD) is a dominantly inherited, fatal neurodegenerative disorder caused by a CAG expansion in exon 1 of the Huntingtin (HTT) gene, which leads to the production of a toxic mutant huntingtin protein (mHTT)." (PMID 39226105, 2024). "Huntington’s disease is a neurodegenerative disordercausedby an expanded polyglutamine stretch near the N-terminus of the huntingtin(HTT) protein, rendering the protein more prone to aggregate." (PMID 38752226, 2024). "Huntington’s disease (HD) results from the expansion of a CAG repeat region in exon 1 of the huntingtin (HTT) gene, situated on chromosome 4, surpassing a pathogenic threshold of at least 37 CAGs." (PMID 38396996, 2024).
Huntington disease (continued). "Huntington’s disease (HD) is a progressive, autosomal-dominantly inherited neurodegenerative disease, caused by a CAG trinucleotide expansion in the huntingtin gene." (PMID 38841617, 2024). "For example, humans with Huntington’s disease carry expanded CAG repeats in their Huntingtin (HTT) gene and aberrant Htt function from conception but only start to exhibit clinical symptoms at early to mid-adulthood." (PMID 38709929, 2024). "Huntington’s disease (HD) is a neurodegenerative genetic disorder resulting from an expanded cytosine-adenine-guanine (CAG) repeat in the huntingtin gene that is clinically characterized by involuntary movements, cognitive decline, and behavioural changes." (PMID 39569347, 2024). "Huntington’s disease (HD) is a hereditary neurological condition that occurs due to an aberrant increase in the number of CAG repeats in the huntingtin (HTT) gene." (PMID 39337461, 2024). "Altered NEAT1 levels were evident in Huntington’s disease cells and postmortem brain tissues, and huntingtin knockdown decreased NEAT1 levels." (PMID 39028820, 2024). "The huntingtin exon-1 (HTTExon-1), which contains a polyglutamine tract, poly-Q, is the main toxic agent in Huntington’s disease." (PMID 39432675, 2024). "In Huntington’s disease (HD) a decrease in palmitoylation of mutant Huntingtin at Cys 214 occurs, resulting in the formation of insoluble protein aggregates." (PMID 39199129, 2024). "AKG2-mediated Sirt2 inhibition also protected against huntingtin-induced toxicity and protein inclusion formation in a primary striatal neuron cell model of Huntington’s disease by decreasing sterol production." (PMID 38474697, 2024). "Multiple connections exist between the transcriptional status of the huntingtin gene in Huntington’s disease (HD) and 14-3-3 proteins." (PMID 38375509, 2024). "The mutant huntingtin protein is known to be present in the major parts of the neurovascular unit in individuals with Huntington's disease." (PMID 38938620, 2024). "Neurodegeneration in Huntington’s disease (HD) is accompanied by the aggregation of fragments of the mutant huntingtin protein, a biomarker of disease progression." (PMID 39737997, 2024). "In literature, it has been demonstrated that Scyllo-Inositol can hinder or decrease the formation of abnormal huntingtin clumps in Huntington’s disease and α-synuclein plaques in Parkinson’s disease." (PMID 38919499, 2024). "Targeting the transcription elongation complex required for mutant huntingtin expression with small molecules ameliorated motor and psychological symptoms in a mouse model of Huntington’s disease." (PMID 38374466, 2024). "Brain region-specific degeneration and somatic expansions of the mutant Huntingtin (mHTT) CAG tract are key features of Huntington's disease (HD)." (PMID 38291334, 2024). "One example of hub proteins called Huntingtin (HTT) that have hundreds of protein interactors and mutations in the HTT gene are associated with Huntington’s disease is well described for a variety of LCRs that contribute to different modes of interaction." (PMID 39074084, 2024). "Huntington’s disease (HD) is caused by genetic factors, specifically through toxic mechanisms within neurons due to the abnormal expansion of CAG repeats in the huntingtin (HTT) protein." (PMID 39457003, 2024). "The imbalance of proteostasis is observed in the formation and accumulation of pathological inclusions, such as α-synuclein in Parkinson’s disease or huntingtin in Huntington’s disease, as well as extracellular β-amyloid plaques in Alzheimer’s disease." (PMID 38542375, 2024). "Huntington’s disease (HD), caused by the expansion of CAG repeats in exon 1 of the huntingtin (Htt) gene, is a pertinent example." (PMID 39000249, 2024). "GCP60 (also called acyl–CoA binding domain containing 3, or ACBD3) levels have also been shown to be elevated in Huntington’s disease due to an expanded polyglutamine repeat sequence in huntingtin." (PMID 38525704, 2024).
Huntington disease (continued). "In Huntington’s disease, mutant huntingtin is the primary aggregating protein, but the aggregation of other proteins, such as TDP43, is likely to further contribute to toxicity." (PMID 39128727, 2024). "The mutant huntingtin protein abnormally interacts with Drp1 and stimulates the enzymatic activity of Drp1, leading to neuronal cell death in mice and humans with Huntington’s disease." (PMID 38550381, 2024). "The selection of Huntington’s Disease patients was based on heterozygosity for the Huntingtin gene, which is an important characteristic for our study." (PMID 39768315, 2024). "Huntington’s disease (HD), a progressive brain disorder caused by 41 or more CAG trinucleotide repeat expansions in huntingtin (HTT), is characterized by mutant HTT protein aggregates in and around the nucleus of neurons." (PMID 38920623, 2024). "Here, we investigated the impact of a C-terminal red fluorescent protein (RFP) tag on the phase separation of huntingtin exon-1 (Httex1), an N-terminal portion of the huntingtin protein that aggregates in Huntington’s disease." (PMID 38141760, 2024). "A high-throughput chemical screen was conducted to identify drugs that lower the toxicity of a protein containing the first exon of Huntington's disease (HD) protein huntingtin (HTT) harbouring 94 glutamines (Htt-Q94)." (PMID 38701619, 2024). "It was recently shown that huntingtin (HTT) repeat expansions with full penetrance, i.e. 40 or more CAG repeats, which normally cause Huntington’s disease (HD), are overrepresented in patients with amyotrophic lateral sclerosis (ALS)." (PMID 39270726, 2024). "In Huntington’s disease, complete knockouts of HTT are embryonic lethal, whereas age-of-onset and life expectancy in rare cases of patients with two expanded alleles are similar to those with only one expanded gene copy." (PMID 38510848, 2024). "The accumulation of invalid structures causes vast groups of neurological disorders, such as α-synuclein in Parkinson’s disease or huntingtin in Huntington’s disease, as well as the extracellular β-amyloid plaques in Alzheimer’s disease." (PMID 38542375, 2024). "Compounds that reduce the protein level of huntingtin and whichare useful in the treatment of Huntington’s disease." (PMID 38996083, 2024). "Huntington’s disease (HD) represents a dominantly inherited neurodegenerative condition featured by the expansion of a CAG short tandem repeat in exon 1 of the huntingtin (HTT) gene." (PMID 38918688, 2024). "Huntington Disease (HD), a devastating hereditary neurodegenerative disorder, is caused by expanded CAG trinucleotide repeats in the huntingtin gene (Htt) on chromosome 4." (PMID 38532785, 2024). "Huntington’s disease (HD) results from altered HTT gene concentration in the nucleus and cytoplasm, primarily due to expanded CAG repeats." (PMID 38317052, 2024). "Huntington disease (HD) is a progressive and devastating neurodegenerative disease caused by expansion of a glutamine-coding CAG tract in the huntingtin (HTT) gene above a critical threshold of ~35 repeats resulting in expression of mutant HTT (mHTT)." (PMID 39386513, 2024). "Huntington’s disease (HD) is a progressive, dominant hereditary ND caused by an abnormal expansion of CAG repeats in the huntingtin gene (HTT)." (PMID 39595812, 2024). "Mutation compromising the normal function of the Huntingtin (HTT) protein is a possible contributor to pathology in Huntington’s disease (HD)." (PMID 39074279, 2024). "In Huntington’s disease (HD), Nup62 and other Nups co-aggregate with cytoplasmic mutant Huntingtin in HD patients, iPSC-derived neurons, and mouse models." (PMID 38254150, 2024). "Here, we address this question for the huntingtin protein, which is involved in Huntington’s disease (HD)." (PMID 38141760, 2024). "Huntington's disease (HD) is a neurodegenerative polyglutamine (polyQ) disease resulting from the expansion of CAG repeats located in the ORF of the huntingtin gene (HTT)." (PMID 39604147, 2024).